CABLES1 (Cdk5 and Abl enzyme substrate 1)
Description:
Cyclin-dependent kinase binding protein. Enhances cyclin-dependent kinase tyrosine phosphorylation by nonreceptor tyrosine kinases, such as that of CDK5 by activated ABL1, which leads to increased CDK5 activity and is critical for neuronal development, and that of CDK2 by WEE1, which leads to decreased CDK2 activity and growth inhibition. Positively affects neuronal outgrowth.
Synonyms: Ik3-1; CABLES; HsT2563; FLJ35924; CABL1
Tractability: PROTAC: ubiquitination databases record sites on it; its protein half-life has been measured.
Gene: Protein-coding gene on chromosome 18 (23,134,564 to 23,260,470, forward strand). Ensembl gene ENSG00000134508.
Subcellular location: Nucleus; Cytoplasm
Subcellular location (Human Protein Atlas): Nuclear bodies; Nucleoplasm
Pathways (Reactome):
Cell Cycle: Cyclin A:Cdk2-associated events at S phase entry; Cyclin E associated events during G1/S transition
Hemostasis: Factors involved in megakaryocyte development and platelet production
Gene Ontology:
Molecular function: protein binding
Biological process: nervous system development; regulation of cell cycle
Cellular component: cytosol; cytoplasm; nucleus
Genetic constraint (gnomAD): Loss-of-function variants: 21 observed, 25.3 expected, observed/expected ratio (o/e) 0.83, 90% interval 0.59 to 1.2. The synonymous counts are far from expectation, so gnomAD's model fits this gene poorly and the ratio says little. Missense variants: 526 observed, 472.36 expected, observed/expected ratio (o/e) 1.11, 90% interval 1.04 to 1.2. Synonymous variants: 286 observed, 218.16 expected, observed/expected ratio (o/e) 1.31, 90% interval 1.19 to 1.45.
Homologues: Orthologues: chimpanzee CABLES1 (99% identical), macaque CABLES1 (97% identical), dog CABLES1 (91% identical), pig CABLES1 (90% identical), rat Cables1 (81% identical), mouse Cables1 (81% identical), tropical clawed frog cables1 (63% identical), zebrafish cables1 (59% identical), guinea pig CABLES1 (57% identical), Drosophila melanogaster CG6191 (31% identical), Caenorhabditis elegans Y71F9B.6 (19% identical). Paralogues in human: CABLES2 (44% identical).
Diseases named in the same sentence as CABLES1 in open-access papers:
CABLES1 is named in the same sentence as 30 diseases in open-access papers, as found by Europe PMC text mining. Sharing a sentence is not in itself a finding about the gene and the disease. The quoted sentences say what the papers report.
ACTHomas (6 papers, 2017 to 2025). "In 55% of ACTHomas cases, loss of expression of CABLES1 has been reported, resulting in impaired sensitivity to glucocorticoids." (PMID 33266265, 2020). "Conclusively, increased expression of 11β-HSD2, HSP90, or TR4, and loss of expression of BRG1 or CABLES1, contribute to the pathogenesis of ACTHomas." (PMID 33266265, 2020). "In fact, mutations in genes codifying for HSP90, TR4, CABLES1, and associated proteins have all been described in corticotrope adenomas and have been associated with features of glucocorticoid resistance, with some of the underlying molecular mechanisms yet to be demonstrated." (PMID 35743266, 2022). "Considering that our patients had sporadic disease presentation, and given that corticotropinomas rarely remain asymptomatic over time, we could assume an incomplete penetrance for CABLES1-associated CD, which could explain the low frequency of these cases." (PMID 28533356, 2017). "CABLES1 is expressed in normal human pituitary cells, but its expression is strongly downregulated in ACTHomas." (PMID 35954322, 2022). "Low or undetectable expression level of CABLES1 is a distinct feature of ACTHomas in pediatric or young adult patients with Cushing’s disease, whereas the gene expresses abundantly in normal corticotrophs." (PMID 33266265, 2020). "Cables1 has been identified as a glucocorticoid-dependent cell cycle modulator in AtT20, a cell line derived from a mouse with ACTHomas." (PMID 33266265, 2020). "Using the murine AtT20 cell line, Cables1 was identified as a glucocorticoid-responsive cell cycle regulatory gene in the tumorigenesis of ACTHomas." (PMID 33266265, 2020). "Notably, CABLES1 is regulated by Akt, which is part of the EGFR signaling pathway, linking EGF and cell cycle regulation and potentially giving CABLES1 a pivotal role in the pathophysiology of corticotrope adenomas." (PMID 35743266, 2022). "The CABLES1 cell cycle regulator participates in the adrenal–pituitary negative feedback, and its expression is reduced in corticotropinomas, pituitary tumors with a largely unexplained genetic basis." (PMID 28533356, 2017). "Conversely, glucocorticoid negative feedback is impaired in ACTHomas, which could be due to the overexpression of 11β-HSD2, HSP90, or TR4, or loss of expression of CABLES1 or nuclear BRG1 proteins." (PMID 33266265, 2020).
adenoma (3 papers, 2021 to 2022). A neoplasm arising from the epithelium. "Despite the low number, given the clinical characteristics of the four described patients (i.e., age and tumor size), it is conceivable that CABLES1 mutations may predispose pediatric patients to the formation of corticotrope adenomas." (PMID 35743266, 2022). "Another gene related to the pathogenesis of ACTH-secreting adenomas is the CABLES1 (Cdk5 and ABL enzyme substrate 1) gene (18q11.2), which negatively regulates cell cycle progression in response to glucocorticoids." (PMID 33515368, 2021). "In fact, CABLES1 levels have been shown to decrease in ACTH-secreting adenomas." (PMID 35743266, 2022). "The role of CABLES1, however, may be overestimated in AtT-20 cells; in fact, CABLES1-knockout mice showed normal pituitary development up to one year, suggesting that other mechanisms may be required for corticotrope adenoma formation." (PMID 35743266, 2022). "None of the CD-causing ACTH-secreting adenomas showed the previously reported SNV in the genes encoding USP48, BRAF, BRG1 and CABLES1." (PMID 35563252, 2022).
colon cancer (3 papers, 2020 to 2023). "In mouse model, genetic inactivation of Cables1 leads to an increased incident of endometrial cancer and colon cancer." (PMID 33949947, 2021). "Early studies demonstrated that CABLES1 is located in chromosome 18q, which is commonly lost in colon cancer, suggesting that CABLES1 played an important role in this malignancy." (PMID 31420702, 2020). "Notably, Cables1-null mice show increased cellular proliferation resulting in endometrial hyperplasia, colon cancer, and oocyte development." (PMID 33949947, 2021).
endometrial cancer (2 papers, 2017 to 2021). Primary or metastatic malignant neoplasm involving the endometrium (mucous membrane that lines the endometrial cavity). "Loss of Cables1 expression is found with high frequency in human cancer such as lung, colon, ovarian, and endometrial cancers." (PMID 33949947, 2021). "Loss of CABLES1 expression is observed with high frequency in human colon, lung, ovarian, and endometrial cancers, and also enhances tumor progression in the ApcMin/+ mouse model and activates the Wnt/β-catenin signaling pathway." (PMID 28583208, 2017).
Obesity (2 papers, 2022 to 2023). Accumulation of substantial excess body fat. "Our results demonstrate that CABLES1 gene expression is downregulated in subjects with T2D and obesity and positively associated with adipocyte glucose uptake, but its ablation in human preadipocytes did not affect adipocyte differentiation or glucose uptake." (PMID 37555665, 2023). "The exploratory data in our study supports an association of CABLES1 with obesity and T2D." (PMID 37555665, 2023). "We used RNAseq analysis of subcutaneous adipose tissue (SAT) from subjects without and with T2D, group-matched for age and BMI, to study the associations of CABLES1 gene expression with clinical markers of obesity and insulin resistance, as well as genes involved in adipose tissue function." (PMID 37555665, 2023). "In this study, we explore the role of CABLES1 in obesity and type 2 diabetes (T2D) in human subcutaneous adipose tissue (SAT)." (PMID 37555665, 2023). "The aim of this study was to investigate the role of CABLES1 in AT metabolism in T2D and obesity, and its potential functional role in adipocyte development and metabolism." (PMID 37555665, 2023). "In SAT, CABLES1 gene expression was 50% (p < 0.001) lower in subjects with obesity compared to lean." (PMID 37555665, 2023). "Cdk5 and Abl enzyme substrate 1 (CABLES1) is a cell cycle regulator that has previously been identified as a candidate gene for obesity-related phenotypes, but little is known about its role in adipose tissue metabolism." (PMID 37555665, 2023). "Besides being implicated in obesity, CABLES1 could potentially also play a role in the development of diabetes through its role as an adaptor protein for CDK5, which has been shown to control diabetogenic actions of PPARG, a master regulator of adipogenesis and crucial for adipocyte function." (PMID 37555665, 2023). "Additionally, in subjects with obesity, CABLES1 gene expression was reduced by approximately 40% (p < 0.001) compared to subjects with overweight." (PMID 37555665, 2023). "The aim of this study was to investigate the role of CABLES1 in SAT in T2D and obesity, and its functional role in adipocyte development and metabolism." (PMID 37555665, 2023). "In conclusion, our findings suggest that CABLES1 gene expression downregulation in SAT in subjects with T2D and obesity may be secondary to metabolic dysregulation, possibly as a protective mechanism." (PMID 37555665, 2023). "Moreover, in cohort 3, which consisted of subjects with obesity that underwent RYGP surgery, there was a trend for increased CABLES1 gene expression by 34% at 104 weeks following RYGP surgery compared to baseline levels (p = 0.08)." (PMID 37555665, 2023).
ovarian carcinoma (2 papers, 2020 to 2024). A malignant neoplasm originating from the surface ovarian epithelium. "The loss of CABLES1 expression was associated with the presence of ovarian cancer in humans, with excessive expression of this gene leading to cancer cell apoptosis." (PMID 32157392, 2020).
pancreatic cancer (2 papers, 2015 to 2023). "Similarly, GGT1 is implicated in pancreatic cancer by genome-wide association studies while AQP5 and CABLES1 enhance tumour progression." (PMID 25944692, 2015). "However, a strong Cables1 expression was found in breast and pancreatic cancers." (PMID 37296610, 2023).
pituitary tumor (2 papers, 2017 to 2025). A benign or malignant neoplasm affecting the pituitary gland. "Given CABLES1 mutational status’s known role in several types of neoplasms, recent research has focused on its relevance in pituitary tumors, including corticotropinomas, where cell cycle dysregulation plays a central role in tumor development." (PMID 40364036, 2025). "All these findings highlight the important role of CABLES1 as a pituitary tumors suppressor gene, as its loss may be linked to dysregulated tumor growth, the failure of negative feedback inhibition, and a potentially more aggressive disease progression." (PMID 40364036, 2025). "The study also proposed that CABLES1 mutations could represent a novel pituitary tumor-predisposing mechanism, particularly affecting interactions with cyclin-dependent kinases (CDKs) and the epidermal growth factor receptor (EGFR) pathway." (PMID 40364036, 2025). "We provide evidence for a role of CABLES1 as a novel pituitary tumor-predisposing gene." (PMID 28533356, 2017). "Our results provide evidence for a role of CABLES1 as a novel pituitary tumor suppressor." (PMID 28533356, 2017).
colorectal cancer (1 paper, 2013). A primary or metastatic malignant neoplasm that affects the colon or rectum. "Reduction of CABLES1 expression was previously observed in colorectal cancers." (PMID 24116037, 2013).
familial isolated pituitary adenoma (1 paper, 2023). "Familial cases represent 5% of PitNEts, which are increasingly recognized as clinicians become more acquainted with familial syndromes, such as familial isolated pituitary adenomas (FIPA), multiple endocrine neoplasia types 1 and 4, X-linked acrogigantism, Carney complex, 3PAs, DICER1, and CABLES1." (PMID 37109772, 2023).
hyperglycaemia (1 paper, 2023). "CABLES1 gene expression in SAT was decreased in T2D by almost 25%, and inversely associated with insulin resistance markers and hyperglycaemia." (PMID 37555665, 2023).
Insulin resistance (1 paper, 2023). Increased resistance towards insulin, that is, diminished effectiveness of insulin in reducing blood glucose levels. "Moreover, in the regression model, the strongest predictor for CABLES1 gene expression levels was BMI, while WHR and the insulin resistance marker HOMA-IR did not contribute significantly." (PMID 37555665, 2023).
osteosarcoma (1 paper, 2017). A usually aggressive malignant bone-forming mesenchymal neoplasm, predominantly affecting adolescents and young adults. "Furthermore, it was reported that miR199a-3p targeting of CABLES1 might play an important role in breast cancer tumor progression and human osteosarcoma, as well as supporting its role as an oncomiR in a pre-leukemic mouse model." (PMID 28583208, 2017).
pituitary adenomas (1 paper, 2017). "Further studies are needed to assess the prevalence of CABLES1 mutations among patients with other types of pituitary adenomas and to elucidate the pituitary-specific functions of this gene." (PMID 28533356, 2017).
serous ovarian cancers (1 paper, 2024). "We further investigated cumulative effects of variants using a gene-wide approach and identified three candidate genes in different analyses: CABLES1 and PPP2R5C in high-grade serous ovarian cancers without and with adjustment for FIGO stage, respectively, and FAM35A in the overall EOC analysis." (PMID 38443389, 2024).
squamous cell carcinoma (1 paper, 2017). A carcinoma arising from squamous epithelial cells. "The CABLES1 protein is widely expressed among tissues and is lost in a variety of human cancers (endometrial, ovarian, colorectal, lung and squamous cell carcinomas)." (PMID 28533356, 2017).
tumor (12 papers, 2015 to 2025). "In several malignancies, such as lung, ovarian, and colorectal cancers, an inactivating mutation in CABLES1 was found to be associated with dysregulated cell cycle progression and increased tumor aggressiveness." (PMID 40364036, 2025). "They identified four potentially pathogenic missense mutations in CABLES1 and found that all patients harboring these mutations presented with macroadenomas, suggesting a link between CABLES1 loss and an increased tumor size." (PMID 40364036, 2025). "Samples from 146 pediatric (118 germline DNA only/28 germline and tumor DNA) and 35 adult (tumor DNA) CD patients were screened for CABLES1 mutations." (PMID 28533356, 2017). "We therefore directly genotyped the tumour samples of the AGO-OVAR 11 study for the most strongly associated variants in CABLES1 (rs77770767, rs28589524, rs6507532, rs4281829), PPP2R5C (rs2448233, rs59784377, rs3783362, rs79999043), FAM35A (rs11492866) as well as for the MGMT variant rs72845444." (PMID 38443389, 2024). "Also, we do not have a firm basis to explain why the loss of function of a ‘generic’ tumor suppressor such as CABLES1 caused a pituitary-specific phenotype in our patients." (PMID 28533356, 2017). "Eight genes were downregulated after S6K1 silencing, but upregulated after S6K2 knock-down, among these the EGFR ligand amphiregulin (AREG), the glutamate-ammonia ligase (GLUL) involved in glutamine synthesis, and the CDK5 and ABL1 enzyme substrate 1 (CABLES1), implicated as a tumour suppressor." (PMID 26698305, 2015). "Indeed, later studies demonstrated that loss of CABLES1 enhanced tumor progression in the Apc(Min/+) mouse model, which may be a consequence of increased activation of the Wnt/β-catenin pathway." (PMID 31420702, 2020). "We then examined the impact of tumour mRNA levels of CABLES1, FAM35A, MGMT and PPP2R5C on PFS in the AGO-OVAR 11 study, and in the publicly available TCGA datasets." (PMID 38443389, 2024). "In our study, CCRL1, SLFN13, SKI, Cables1, and DCHS1 were all shown to be regulated under TMZ-promoted dormancy and, besides tumor cells, to be expressed by endothelial cells and tumor-associated microglia/macrophages." (PMID 37296610, 2023). "Concerning the expression of the markers in tumor-associated microglia/macrophages and in accordance with our findings, an expression of SKI, Cables1, and DCHS1 was also described by previous studies." (PMID 37296610, 2023). "It was also shown that CABLES1 overexpression induced apoptosis and inhibited cell growth at least in part through p21 stabilization, further consolidating that CABLES1 acts as a tumor suppressor." (PMID 31420702, 2020). "It is generally thought that Cables1 is a tumor suppressor gene." (PMID 33949947, 2021). "The tumor suppressor activity of CABLES1 is inhibited by 14-3-3 or AKT-mediated phosphorylation." (PMID 28533356, 2017).
cancer (7 papers, 2017 to 2023). A tumor composed of atypical neoplastic, often pleomorphic cells that invade other tissues. "In multiple types of cancer, a very frequent loss of Cables1 has been observed which implies a potential suppressive effect on tumorigenesis." (PMID 37296610, 2023). "CABLES1 codifies for a tumor suppressor often altered in many different types of cancer." (PMID 35743266, 2022).
infection (1 paper, 2024). The state of being infected such as from the introduction of a foreign agent such as serum, vaccine, antigenic substance or organism. "Given the significant reduction in RCAS(J)GFP infection observed in Cables1 knockout cells, we selected Cables1 for further investigation." (PMID 39307305, 2024). "Fluorescence intensity measurements at three days post-infection (dpi) showed that the knockout of DHFR, CDK1, and Cables1 inhibited RCAS(J)GFP infection." (PMID 39307305, 2024). "Notably, a reduction of 40%, 36%, and 44% in RCAS(J)GFP infection rates was observed in DHFR, CDK1, and Cables1 knockout lines, respectively, compared to that in WT DF-1 cells." (PMID 39307305, 2024). "Similarly, flow cytometry results demonstrated that at three dpi with an MOI of 0.01, the infection rates of RCAS(J)GFP were 22%, 23%, 20%, and 35% in DHFR, CDK1, and Cables1 knockout, and WT DF-1 cells, respectively." (PMID 39307305, 2024).
CABLES1 also shares sentences with these, for which no sentence is quoted: acromegaly (1 paper); Alzheimer disease (1); attention deficit-hyperactivity disorder (1); autism (1); bladder cancer (1); diabetes (1); neurodegenerative disease (1); neurofibromatosis type 1 (1); Pas (1); tuberous sclerosis (1); type 2 diabetes (1).